GAA (alpha glucosidase)
Diseases named in the same sentence as GAA in open-access papers (continued):
Sharing a sentence is not in itself a finding about the gene and the disease.
type 2 diabetes (65 papers, 2007 to 2026). "The role of Andrographolides, one of its major phytoconstituents has been reported to have inhibitory effect on the rat and human hepatic cytochrome P450 and the alpha-glucosidase and alpha-amylase enzymes that cause type 2 diabetes." (PMID 19216765, 2009). "Although Acarbose and Voglibose are commonly used drugs for type 2 diabetes treatment due to their ability to inhibit alpha-amylase and alpha-glucosidase enzymes, they have the drawback of causing numerous side effects such as gastrointestinal discomfort and diarrhea." (PMID 39241083, 2024). "Alpha-glucosidase and α-amylase inhibition could potentially be used as an effective therapy for post-prandial hyperglycaemia linked to type 2 diabetes." (PMID 23039079, 2012). "Alpha-glucosidase inhibitors are one of the therapies used for treating type 2 diabetes by inhibiting the absorption of carbohydrates in the gastrointestinal tract." (PMID 39810844, 2025). "Acarbose is an alpha-glucosidase inhibitor used for the management of glycemic control in patients with type 2 diabetes." (PMID 40363834, 2025). "Until now, pharmaceutical treatments for type 2 diabetes consist of biguanides, sulfonylureas, and alpha-glucosidase inhibitors, in addition to semaglutide and tirzepatide, which were recently included in the treatment of type 2 diabetes and obesity." (PMID 38398573, 2024). "Acarbose is an alpha-glucosidase inhibitor approved for the treatment of type 2 diabetic postprandial hyperglycaemia; typically used as monotherapy in Asia and as an add-on treatment in the rest of the world." (PMID 38842918, 2024). "Alpha-glucosidase inhibitors are a group of drugs commonly used to treat type 2 diabetes, either as a monotherapy or in combination with other antidiabetic agents." (PMID 39728150, 2024). "Other FDA approved medications for the treatment of type 2 diabetes, among which biguanides, alpha-glucosidase inhibitors (α-GIs), incretin-based drugs, GLP-1 receptor agonists and DPP-4 inhibitors also affect the gut microbiota." (PMID 38596222, 2024). "Among the several promising targets for treating type 2 diabetes, alpha-glucosidase has become important in natural product research." (PMID 39795116, 2024). "Given that metformin, SGLT2 Is, GLP‐1 RAs and alpha‐glucosidase inhibitors may be beneficial for weight loss, while sulfonylureas, thiazolidinediones and insulin may be associated with weight gain, weight loss observed in type 2 diabetes patients nowadays are more likely to result from medication." (PMID 36756713, 2023). "Synthetic alpha-glucosidase inhibitors (acarbose, voglibose, and miglitol) are therapeutics used for the treatment or prevention of type 2 diabetes and its complications." (PMID 37367662, 2023). "Inhibition of alpha-glucosidase reduces carbohydrate digestion, consequently decreasing carbohydrate content in blood, which improves human health outcomes regarding type 2 diabetes." (PMID 36827131, 2023). "Peptides of natural origin are promising compounds that can serve as alpha-glucosidase inhibitors in the treatment of type 2 diabetes." (PMID 37630730, 2023). "The inhibition of alpha-glucosidase is critical for the effective management of type-2 diabetes, which is distinguished by hyperglycemia, resistance to insulin, and insufficient insulin secretion." (PMID 38002116, 2023). "GAA has been identified as the most important enzyme in the prevention and treatment of Type 2 diabetes." (PMID 35214895, 2022). "The antidiabetic activity of C. didymus was evaluated using the alpha glucosidase enzyme, one of the key enzymes involved in Type II diabetes." (PMID 36234800, 2022). "Current treatment includes insulin therapy in Type 1 diabetes and single or multiple combinations of sulfanylurea, diazolidediones, biguanides, alpha glucosidase inhibitors, meglitinides and insulin in Type 2 diabetes." (PMID 35729613, 2022).
type 2 diabetes (continued). "This plant has been reported to possess alpha-glucosidase inhibitory activity, a key enzyme corresponding to type 2 diabetes." (PMID 34961160, 2021). "Another meta-analysis suggested that alpha-glucosidase inhibitors (alpha-GIs) can attenuate the CIMT progression in patients with impaired glucose tolerance or type 2 diabetes mellitus (T2DM)." (PMID 32454794, 2020). "More and more studies have been conducted to examine inhibition effects on alpha glucosidase and alpha amylase of pu-erh tea, aimed at exploring physiological and functional results for the prevention and treatment of type 2 diabetes." (PMID 31455758, 2019). "Alpha-glucosidase inhibitors (AGIs) have been shown to reduce incident type 2 diabetes but their impact on cardiovascular (CV) disease remains controversial." (PMID 31623625, 2019). "Fucoidan, a sulfated polysaccharide also found in various species of brown algae, lowers alpha-glucosidase activity in vitro, blood glucose in db/db mice, and glycated hemoglobin and glucagon-like peptide-1 in type 2 diabetes patients." (PMID 31242682, 2019). "Cai X, Han X, Luo Y, Ji L. Comparisons of the efficacy of alpha glucosidase inhibitors on type 2 diabetes patients between Asian and Caucasian." (PMID 29527102, 2018). "Examples of predicted applicable diseases of sinomenine are adiposity and type II diabetes mellitus, implying that sinomenine is effective for treatment of adiposity and type II diabetes mellitus based on the target proteins: GAA, OPRM1, OPRD1, OPRK1." (PMID 30046160, 2018). "Zhang L, Chen Q, Li L, Kwong JS, Jia P, Zhao P, Wang W, Zhou X, Zhang M, Sun X. Alpha-glucosidase inhibitors and hepatotoxicity in type 2 diabetes: a systematic review and meta-analysis." (PMID 29527102, 2018). "We compared the effects of the DPP-4i, sitagliptin, and the alpha-glucosidase inhibitor, voglibose, on LV diastolic function in patients with type 2 diabetes." (PMID 26084668, 2015). "This enzyme plays a major role in the glycogen metabolism and because of its effect on the absorption of sugars from the gut, alpha-glucosidase inhibitors are used in the treatment of type 2 diabetes." (PMID 25071839, 2014). "In the treatment of type 2 diabetes, alpha-glucosidase inhibitors (AGIs; including acarbose, miglitol, voglibose) were recommend by guidelines for glucose control in type 2 diabetes." (PMID 24236131, 2013). "L. sylvestris has been shown to exert pharmacological properties such as antioxidant, alpha glucosidase inhibition and insulin secretagogue properties, thus making it a notable plant to be explored for its potential antidiabetic properties in models of type 2 diabetes." (PMID 39070783, 2024). "Of note, the medications for type 2 diabetes which the participants were taking at baseline in this study were either metformin, sulfonylureas, thiazolidinediones or insulin (with an exception of only 2 participants taking alpha‐glucosidase inhibitors)." (PMID 36756713, 2023). "We observed that kombucha inhibited alpha-glucosidase activity in the context of type-2 diabetes, indicating that it may have the ability to reduce dietary sugar absorption." (PMID 38002116, 2023). "Reducing the activity of alpha-glucosidase is essential for managing and treating type-2 diabetes." (PMID 38002116, 2023). "In this study, compounds of P. betle were screened to investigate the inhibitory action of alpha-amylase and alpha-glucosidase against type 2 diabetes through molecular docking, molecular dynamics simulation, and ADMET (absorption, distribution, metabolism, excretion, and toxicity) analysis." (PMID 35889399, 2022). "Acarbose, as an alpha-glucosidase inhibitor, is widely used clinically to treat type II diabetes." (PMID 36419063, 2022). "However, numerous studies in recent years have shown that alpha-glucosidase enzyme inhibitors are critical in the proper management of Type 2 diabetes." (PMID 34832691, 2021).
type 2 diabetes (continued). "In addition, the concentration-dependent inhibitory properties of the prepared PDA@CNTs on the activity of the alpha glucosidase enzyme showed their possible use as a drug in the treatment of Type 2 diabetes." (PMID 34832691, 2021). "The lipid-lowering effect of anagliptin was first demonstrated in a phase III trial comparing anagliptin to placebo as a single agent or with concurrent anti-diabetic treatment, such as alpha-glucosidase inhibitors, biguanide, sulfonylurea, or thiazolidine in type 2 diabetic patients for 12 weeks." (PMID 29435776, 2018). "Alpha glucosidase inhibitor (GI) prevents the digestion of carbohydrates including starch and table sugar, attenuates postprandial hyperglycemia and delays the development of type 2 diabetes in patients with IGT." (PMID 25074318, 2014). "Alpha glucosidase inhibitor (GI) attenuates postprandial hyperglycemia (PPH) and reduces the risk of cardiovascular events in patients with impaired glucose tolerance or type 2 diabetes." (PMID 25074318, 2014). "This study will extend the current data on CyclosetTM safety, tolerability and efficacy in individuals with type 2 diabetes to include its effects in combination with thiazolodinediones, insulin secretagogues, metformin, alpha-glucosidase inhibitors and exogenous insulin regimens." (PMID 17592632, 2007). "Inhibitors of DPP-IV and alpha-glucosidase enzymes are the key targets for the pharmaceutical sector for development of drugs to prevent or to control type 2 diabetes [T2D]." (PMID 36827131, 2023). "Acarbose, a pseudo-tetrasaccharide used to manage type 2 diabetes and a candidate drug in clinical trials targeting human aging based on its ability to improve health and lifespan in animal models, is a potent competitive inhibitor of mammalian GAA, but is less effective against yeast GAA." (PMID 31901900, 2020). "Other anti-diabetic drugs, such as dipeptidyl peptidase-4 (DPP-4) and alpha-glucosidase inhibitor could also improve endothelial function in patients with type 2 diabetes, rosiglitazone could improve angiogenic potential of diabetic ECs and proangiogenic cells (PACs)." (PMID 27316923, 2016). "The alpha-glucosidase inhibitor acarbose is approved for the treatment of type 2 diabetes (T2D)." (PMID 38842918, 2024). "In addition, a considerable number of patients were being treated with sulfonylureas and/or alpha glucosidase inhibitors, and one patient in each group was being treated with pioglitazone, an insulin-sensitizing drug that has been shown to reduce VFA in patients with type 2 diabetes." (PMID 31192262, 2019). "An earlier meta-analysis of randomised controlled trials of alpha-glucosidase inhibitors suggested that they may prevent the progression if carotid intima thickness in patients with IGT or type 2 diabetes, but our CV meta-analysis suggests this does not translate into fewer CV events." (PMID 31623625, 2019).
Hyperglycemia (47 papers, 2010 to 2025). An increased concentration of glucose in the blood. "Synthetic alpha-amylase and alpha-glucosidase inhibitors can improve blood glucose control in diabetic patients by effectively reducing the risk of postprandial hyperglycemia." (PMID 37630730, 2023). "Although the exact mechanism remains uncertain, the improvement of hypoadiponectinemia and hyperglycemia is considered to be associated with the chronic suppression of postprandial blood glucose elevation by alpha-glucosidase inhibition." (PMID 20181067, 2010). "Alpha-glucosidase is an enzyme that is commonly associated with hyperglycaemia in type 2 DM." (PMID 36372924, 2023). "Alpha-glucosidase inhibitors (α-GIs) improve postprandial hyperglycemia (PPHG) and may have favorable effects on associated cardiovascular disease." (PMID 23777506, 2013). "Likewise, inhibition of the alpha-glucosidase and alpha-amylase could delay the release of free glucose in the blood, and hyperglycemia associated with type 2 can be managed in this way." (PMID 33916198, 2021). "Sulfonylureas, biguanides, alpha-glucosidase inhibitors, and thiazolidinediones are examples of newer-generation medications having high efficacy in decreasing hyperglycemia as a result of scientific and technological advancements." (PMID 39453501, 2025). "1-deoxynojirimycin and DAB are alpha-glucosidase inhibitors derived from the Mulberry plant for hyperglycemia treatment." (PMID 40332944, 2025). "Two genes are targets of drugs approved for treatment of hyperglycemia: alpha glucosidase (GAA), targeted by miglitol, and SLC5A2 (aka SGLT2), targeted by dapagliflozin." (PMID 38199042, 2024). "Plant-derived compounds have been identified as effective alpha-glucosidase inhibitors, crucial in modulating postprandial hyperglycemia." (PMID 39065741, 2024). "Along with alpha glucosidase inhibitors, these produce significant control of the post-prandial hyperglycaemia." (PMID 38428138, 2024). "Plant compounds like Taxumariene F, Akebonoic acid, Morusin, Rhaponticin, Procyanidin A2, Alaternin, Mulberrofuran K, and Psoralidin show potential for managing hyperglycemia by targeting alpha-glucosidase enzymes." (PMID 39065741, 2024). "Inhibitors of alpha-glucosidase play a crucial role in managing postprandial hyperglycemia (PPHG) in diabetic patients because inhibiting the activity of the alpha-glucosidase enzyme decreases starch hydrolysis." (PMID 39108648, 2024). "Alpha-amylase and alpha-glucosidase are the carbohydrate hydrolyzing enzymes found inside the human body that lead to postprandial hyperglycemia." (PMID 36677655, 2023). "A low GI meal has been shown to reduce postprandial hyperglycaemia and the incremental benefit is similar to that offered by pharmacological agents such as alpha-glucosidase inhibitors that also target postprandial glycaemia." (PMID 36474545, 2022). "Of these, alpha-glucosidase inhibitors are taken just before a meal, as evidenced by past studies, and are particularly useful for reducing postprandial hyperglycemia." (PMID 35742001, 2022). "As a result, the inhibition of alpha-glucosidase activity can result in a substantial delay in post-prandial hyperglycemia and a favorable impact on insulin resistance and glycemic index regulation." (PMID 36204125, 2022). "This study aims to identify the roles of exo-β-glucan (EPS-BG) and endo-β-glucan (ENS-BG) extracted from Ganoderma lucidum (GL) in inhibiting the alpha-glucosidase enzyme, a target mechanism for postprandial hyperglycaemia regulation." (PMID 36091430, 2022). "Antidiabetic medications that target postprandial hyperglycemia such as alpha-glucosidase inhibitors (AGI) and glucagon-like peptide 1 (GLP-1) agonists can lower cardiovascular event rates in T2DM, partly through reduction of plasma LDL cholesterol levels." (PMID 34669756, 2021).
Hyperglycemia (continued). "Alpha-glucosidase inhibitors represent a group of antidiabetic drugs that regulate postprandial hyperglycemia through inhibition of carbohydrates digestion in the small intestine and thus hamper the diet associated with acute glucose excursion." (PMID 33335883, 2020). "The current study was carried out to evaluate the in-vitro and in-vivo efficiency of alpha glucosidase inhibitor of marine actinobacteria in the control of postprandial hyperglycaemia." (PMID 29755552, 2018). "Voglibose inhibits intestinal alpha-glucosidase activity and generally attenuates hyperglycemia by lowering postprandial hyperglycemia." (PMID 27802313, 2016). "Voglibose, an alpha-glucosidase inhibitor, inhibits the breakdown of disaccharides into monosaccharides by acting competitively on the activities of an alpha-glucosidase, controlling postprandial hyperglycemia." (PMID 27802313, 2016). "Scientific and technological advances have witnessed the development of newer generation of drugs like sulphonylureas, biguanides, alpha glucosidase inhibitors, and thiazolidinediones with significant efficacy in reducing hyperglycemia." (PMID 26273667, 2015). "The use of alpha glucosidase inhibitor treatment in control of rise in the postprandial glucose level is desirable as it constitutes a noninvasive mechanism for controlling hyperglycemia." (PMID 21792369, 2012). "Alpha-glucosidase inhibitors (AGIs) are a class of widely used antidiabetic drugs that inhibit alpha-glucosidase in the small intestinal mucosa, delaying carbohydrate absorption and reducing postprandial hyperglycemia." (PMID 39751859, 2024). "Alpha-glucosidase plays an essential role in the regulation of blood glucose, and the inhibition of this enzyme could suppress postprandial hyperglycaemia." (PMID 36372924, 2023). "The drugs inhibit the alpha-glucosidase enzyme that hydrolases carbohydrates into α-glucose in the small intestine, thus delaying glucose absorption into the bloodstream and suppressing postprandial hyperglycaemia." (PMID 36372924, 2023). "Apple peel contains alpha-glucosidase inhibition, and apple flesh contains amylase inhibitors, which may be a benefit for managing hyperglycemia while reducing side effects." (PMID 35742001, 2022). "The in vitro assays demonstrated that the inhibition of alpha-amylase and alpha-glucosidase might be one of the mechanisms of action exhibited by the extract of this plant to control and prevent postprandial hyperglycemia." (PMID 33430115, 2021). "Alpha-glucosidase inhibitors which mainly lower postprandial hyperglycemia may have greater effectiveness in Asians than Caucasians and can be a first-line drug according to the guideline of T2DM in China." (PMID 29301579, 2018). "Besides, C. caudatus is found to have a good inhibitory effect against enzyme alpha-glucosidase, thus attenuates the intestinal glucose uptake, and suppresses postprandial hyperglycemia." (PMID 26713097, 2015). "Alpha-glucosidase inhibitors, such as acarbose, act via inhibiting disaccharide hydrolyzing enzymes in the small intestine, thereby decreasing glucose absorption and improving control over postprandial hyperglycemia." (PMID 24932223, 2014). "Based on the results obtained with intestinal alpha-glucosidase, it should be expected that in vivo acarbose is more effective then RGPE in reducing postprandial hyperglycemia." (PMID 20799969, 2010). "In this study, the alpha-glucosidase activity (maltase, sucrase, and lactase) decreased after COS treatment, indicating that COS slowed down carbohydrate decomposition and reduced postprandial hyperglycemia." (PMID 38647883, 2022). "Pears may serve as a suitable alternative regulating postprandial hyperglycemia by inhibiting alpha-amylase and alpha-glucosidase without any significant side effects." (PMID 34470625, 2021).